C5AR1 (complement C5a receptor 1)
Diseases named in the same sentence as C5AR1 in open-access papers (continued):
Sharing a sentence is not in itself a finding about the gene and the disease.
myocardial infarction (3 papers, 2021 to 2025). Gross necrosis of the myocardium, as a result of interruption of the blood supply to the area, as in coronary thrombosis. "These include C1qa, C1qb, and C1qc, all components of the membrane attack complex, as well as C5ar1, the receptor for the complement anaphylatoxin 5a, which can stimulate immune cells in myocardial infarct models." (PMID 39202335, 2024). "In the treatment of myocardial infarction, we have obtained key targets of Yixinyin, which are ALDH2, C5AR1, FOS, IL1B, TLR2, TXNRD1." (PMID 34799616, 2021).
pancreatic cancer (3 papers, 2021 to 2023). "Another candidate marker, C5AR1, is expressed in both myeloid cells and non-myeloid cells and has been associated with increased recruitment and polarisation of macrophages to an M2 state in CRCLM and pancreatic cancer LM." (PMID 39516397, 2023).
pancreatic ductal adenocarcinoma (3 papers, 2023 to 2025). An infiltrating adenocarcinoma that arises from the epithelial cells of the pancreas. "We investigated the functions of complement 5a (C5a) and its receptors, C5aR1 and C5aR2, in forming the C5a-C5aR1 and C5a-C5aR2 signaling axes in the immune TME of pancreatic ductal adenocarcinoma (PDAC)." (PMID 41044172, 2025).
prion disease (3 papers, 2018 to 2022). A transmissible disease that is caused by a protein that is able to induce abnormal folding of normal cellular proteins, leading to characteristic spongiform brain changes, which are associated with neuronal loss without an inflammatory response. "To investigate the role of some of these proteins in prion disease of the CNS, we infected mice deficient in DAMP receptor genes Tlr2, C3ar1, and C5ar1 with 22L scrapie." (PMID 30596651, 2018). "Though complement components C3 and C5 are not required for prion pathogenesis, the G protein-coupled receptors C3aR1 and C5aR1 might influence prion disease by interacting with other unidentified ligands to elicit a response." (PMID 30596651, 2018). "Surprisingly, deletion of C5, the protein that is cleaved to generate C5a, does not affect scrapie survival or vacuolation, and our results indicate deletion of the C5a receptor C5ar1 also has no measurable effect on prion disease." (PMID 30596651, 2018). "Interestingly, depletion of any of the DAMP receptor genes Tlr2, C3ar1, and C5ar1 in a prion mouse model only led to a slightly increased survival in the Tlr2-model, while C3ar1, and C5ar1 did not influence prion disease course." (PMID 36230910, 2022).
prostate carcinoma (3 papers, 2020 to 2025). A carcinoma that arises from epithelial cells of the prostate gland. "C5aR1 mRNA levels were significantly increased in severe hypoxia (<0.1% O2) but not milder levels (1% O2) in colorectal and glioblastoma cancer cells (showing similar effect in ovarian and prostate cancer cells)." (PMID 40695778, 2025). "Additionally, four novel targets were predicted (IGF2R, C5AR/C5AR1, RAB7, and SETD2) which are all involved in molecular pathways closely connected to prostate cancer, with some having been recently proposed as suitable targets for other types of cancers." (PMID 38983753, 2024).
psoriatic arthritis (3 papers, 2017 to 2025). Joint inflammation associated with psoriasis. "The C5a–C5aR1 axis plays a pivotal role in neutrophil recruitment and activation in inflammatory diseases like rheumatoid arthritis and psoriatic arthritis." (PMID 41550949, 2025).
Shock (3 papers, 2018 to 2024). The state in which profound and widespread reduction of effective tissue perfusion leads first to reversible, and then if prolonged, to irreversible cellular injury. "Moreover, C5aR1-knock-down animals has a lower MPO level in lung of mice with polytrauma and hemorrhagic shock." (PMID 38165570, 2024).
uveitis (3 papers, 2017 to 2025). An inflammatory process affecting a part of or the entire uvea. "In a mouse model of experimental autoimmune uveitis (EAU) less severe uveitis in C3aR1/C5aR1-double KO mice than control mice was evident, involving reduced T cell response." (PMID 39775695, 2025).
aneurysm (2 papers, 2022 to 2024). Bulging or ballooning in an area of an artery secondary to arterial wall weakening. "Human aortic samples were collected from MFS and non-MFS aneurysm patients to study complement factor gene expression C1R, C1S, C3AR1, and C5AR1 and SMC gene ACTA2." (PMID 36279189, 2022).
Autoimmunity (2 papers, 2020 to 2022). The occurrence of an immune reaction against the organism's own cells or tissues. "In experimental anti-MPO glomerulonephritis, genetic or pharmacologic C5aR1 targeting resulted in attenuated TH1 immunity and increased frequency of regulatory T cells (Tregs) eventually mitigating autoimmunity to MPO." (PMID 35958588, 2022). "C5aR1 modulates development of autoimmunity to MPO, with C5ar1−/− mice relatively protected from T cell mediated disease, as dendritic cells lacking the C5aR1 are not able to fully activate anti-MPO T cells." (PMID 32373109, 2020).
bacteremia (2 papers, 2018 to 2024). "In clear contrast to the response of C5-deficient mice, the mice lacking C5aR1 displayed significantly higher survival rates and lower levels of bacteremia than WT mice under conditions of infection with 105 CFU." (PMID 29362231, 2018). "One particularly striking finding is that C5aR1−/− mice as well as WT mice treated with PMX205 displayed a significantly lower bacterial burden than the corresponding WT controls during the course of disease despite comparable levels of bacteremia at 3 h." (PMID 29362231, 2018).
bacterial meningitis (2 papers, 2020 to 2021). Inflammation of the membranes surrounding the brain and spinal cord due to a bacterial infection. "On the other hand, C5aR1 signaling is associated with poor outcome after subarachnoid hemorrhage in human patients as well as in rodent models, and C5a-dependent chemotactic activity is linked to brain damage and disease severity in bacterial meningitis." (PMID 33613523, 2020).
bladder infection (2 papers, 2017 to 2022). "Collectively, these results demonstrate that C5aR deficiency reduces bladder infection rate and leads to reduced bladder bacterial load (with up to 1.5 log reduction) and less severe tissue injury, thus supporting a pathogenic role for C5aR1 in acute cystitis." (PMID 35433513, 2022). "In this study, we report that the C5a/C5aR1 axis also plays a pathogenic role in acute bladder infection." (PMID 35433513, 2022). "Given the critical role of the bladder infection in ascending UTI, C5aR1-associated bladder infection could potentially contribute to renal infection." (PMID 29263309, 2017). "Taken together, these results demonstrate that blockade of C5aR1 provides protection against acute bladder infection." (PMID 35433513, 2022). "To determine the role of C5aR1 in acute cystitis, we induced the infection in WT and C5ar1-/- mice and assessed the bladder infection rate and severity of bladder infection." (PMID 35433513, 2022). "We therefore sought to assess whether blockade of C5aR1 could provide protection against acute bladder infection." (PMID 35433513, 2022). "C5ar1-/- mice displayed a lower bladder infection rate compared with WT mice (50% vs. 80%)." (PMID 35433513, 2022).
cardiac insufficiency (2 papers, 2017 to 2021). "Studies have shown that in the absence of C5aR1, the levels of IL-1 beta and IL-6 decreased in the plasma of mice with cardiac insufficiency are reduced." (PMID 34799616, 2021).
complement deficiency (2 papers, 2018 to 2024). A genetic deficiency of any of the component of the complement system (including the classical, alternative, and terminal pathway components), that can either be acquired or inherited. "While broad complement deficiency did not drastically affect lung larvae burden, our study evidenced a drastic reduction of viable parasites count in BALF in C5aR1-/- mice, but not in C5aR2-/- or in C5aR1/2-/- double knockout mice." (PMID 39628481, 2024).
cutaneous squamous cell carcinoma (2 papers, 2020 to 2025). "A recent study suggests that C3b could impact tumorigenesis during chronic skin inflammation, in cutaneous squamous cell carcinoma (cSCC) model, but independently of C3aR or the terminal pathway (C5a/C5aR1/C5aR2 and MAC generation), likely by influencing tumor associated macrophages." (PMID 33113844, 2020).
cyst (2 papers, 2022 to 2024). A sac-like closed membranous structure that may be empty or contain fluid or amorphous material. "Increased C5a formation and C5aR1 activation in tubular cells promotes cyst growth, offering a new therapeutic target." (PMID 38912583, 2024).
epidermolysis bullosa acquisita (2 papers, 2019 to 2022). "More downstream, epidermolysis bullosa acquisita is likely to be C5aR1-dependent, since C5aR1-deficient animals were protected against development of epidermolysis bullosa acquisita." (PMID 31293600, 2019). "In summary, these experimental models demonstrate involvement of CP- and AP-activation and C5a-C5aR1-axis activation in the development of epidermolysis bullosa acquisita." (PMID 31293600, 2019). "While C5aR1 has been shown to exert a strong pro-inflammatory effect in these mouse models, both pro- and anti-inflammatory effects of C5aR2 have been reported in mouse models of BP and BP-like epidermolysis bullosa acquisita." (PMID 36466856, 2022).
inflammatory bone diseases (2 papers, 2018 to 2022). "Therefore, a deeper understanding of osteoblast responses to inflammatory stimuli, mimicked here by the application of C5aR1 and TLR2 ligands, is key to managing inflammatory bone diseases in future." (PMID 30247799, 2018).
kidney damage (2 papers, 2025). "In other models, including FA-induced nephropathy and the 5/6 nephrectomy model, increased C5aR1 expression was observed in infiltrating immune cells." (PMID 40519169, 2025). "In addition to elevated levels of prothrombotic factors such as tissue factor (F3), fibrinogen α chain (Fga) and Pai1 gene expression, complement activators C3, C1qa, and C5ar1 were upregulated in adenine‐ and folic acid‐induced nephropathy." (PMID 41324413, 2025).
kidney infection (2 papers, 2017 to 2022). "In addition to the J96 strain, we also observed C5aR1-dependent bacterial colonization in other human pyelonephritis strains: IH11128 (lack of P fimbriae) and CFT073 (data not shown)." (PMID 29263309, 2017).
metastatic disease (2 papers, 2021 to 2024). "In some studies, the presence of the C5aR1 was associated with a higher proliferation rate, metastatic disease, advanced tumour stage, and poor patient outcomes." (PMID 33606748, 2021).
nephritis (2 papers, 2016 to 2025). Inflammation of renal tissue. "Likewise, similar C5 and C5AR1 frequencies were observed amongst IgAV patients stratified according to IgAV severity (presence/absence of nephritis)." (PMID 40717085, 2025).
osteoporosis (2 papers, 2022). A condition of reduced bone mass, with decreased cortical thickness and a decrease in the number and size of the trabeculae of cancellous bone (but normal chemical composition), resulting in increased fracture incidence. "Because C5a is generated downstream of C3 in the complement cascade, it can be suspected that the C5a/C5aR1 axis also plays a role in osteoporosis-associated inflammatory processes." (PMID 36246887, 2022). "Similarly, mice with an osteoclast-specific deletion of C5aR1 developed osteoporosis after OVX due to increased osteoclast formation and activity." (PMID 36246887, 2022). "By contrast, C5aR1LysM-Cre mice developed OVX-induced osteoporosis similarly as C5aR1fl/fl mice, suggesting that C5aR1 on osteoclasts does not directly mediate increased bone resorption." (PMID 36246887, 2022).
ovarian tumor (2 papers, 2019 to 2021). "Genetic or pharmacological inhibition of C3 or C5aR1 results in smaller and poorly vascularized ovarian tumors in vivo, and C5a is able to promote endothelial cell tube formation and migration." (PMID 34359708, 2021). "Agonists of C5aR1 and C3aR increase ovarian tumor cell proliferation, migration, and invasion, suggesting that receptor antagonists could be used to block cancer growth." (PMID 34359708, 2021). "Autocrine stimulation of C5aR1 and C3aR upon C5a and C3a binding leads to PI3K/AKT signaling and regulates the proliferation and invasiveness of ovarian tumor cells." (PMID 31001273, 2019).
periodontal disease (2 papers, 2020 to 2025). "C5a was found to increase the release of IL-1β and IL-6 when added to Aβ-primed human monocytes in vitro and C5aR1 antagonists have been found to reduce proinflammatory cytokines (IL-1β) in periodontal disease." (PMID 33239010, 2020).
septic shock (2 papers, 2020 to 2021). Shock caused by infection; frequently caused by gram negative bacteria, although some cases have been caused by other bacteria, viruses, fungi, and protozoa; characterized by fever, chills, tachycardia, tachypnea, and hypotension. "In a previous study, we showed a significant reduction of the C5aR1 on neutrophils from septic shock patients and simultaneously increased plasma levels of a circulating form of C5aR1, suggesting that cells lose their receptors through MV shedding." (PMID 32983087, 2020).
stable angina (2 papers, 2021 to 2025). "By the integration of the DEGs of healthy/MI and unstable angina/MI, the potential targets of Yixinyin for the treatment of MI (ALDH2, C5AR1, CFOS, IL1B, TLR2, TRXR1) have been obtained." (PMID 34799616, 2021).
steatosis (2 papers, 2014 to 2023). Increased lipid within the cytoplasm of cells. "Overall, blockade of C5aR1 resulted in a reduction of hepatic fibrosis, inflammatory response, and steatosis in NASH mice." (PMID 37227481, 2023). "Taken together, we conclude that loss of C5aR1 inhibits the progression of NASH, including resistance to steatosis, inflammation, and fibrosis." (PMID 37227481, 2023).
type 1 diabetes (2 papers, 2021 to 2023). "GSEA analysis indicates that the high expression groups of ALDH2, C5AR1, CFOS, IL1B, TLR2, TRXR1 jointly participate in the pathways of viral myocarditis, VEGF signaling pathway and type I diabetes mellitus associated with MI." (PMID 34799616, 2021).
urinary tract infection (2 papers, 2017 to 2018). "Recent work in a murine model of ascending urinary tract infection has suggested that C5a/C5aR1 interactions play a pathogenic role in the development of renal infection through enhancement of bacterial adhesion/colonization to renal tubular epithelial cells (RTECs)." (PMID 29765378, 2018).
abscesses (1 paper, 2015). "The larger abscesses in the kidneys of C5aR1−/− and C5aR2−/− mice induced higher levels of tissue destruction than the small emerging abscesses of wild type mice." (PMID 26512700, 2015). "More interesting was the observation that genetic deletion of either C5aR1 or C5aR2 resulted in enhanced production of neutrophil chemoattractant CXCL1 and in the infiltration of neutrophils into the infected kidneys, accelerated abscess formation and increased tissue damage." (PMID 26512700, 2015).
adenoma (1 paper, 2020). A neoplasm arising from the epithelium. "H&E staining showed that adenoma formation was accompanied by diffuse immune cells infiltration in the colons of WT, C3-deficient, and C5ar2-deficient mice, while more mucosa-associated lymphoid tissues suspected as tumors were observed in C5- and C5ar1-deficient mouse colons." (PMID 32754267, 2020).
alcoholic hepatitis (1 paper, 2023). Acute hepatitis resulting from ingestion of alcohol. "C5AR1 expression is increased in the liver of patients with alcoholic hepatitis, and is believed to contribute to alcohol-induced inflammation and liver injury." (PMID 36899881, 2023).
allergic dermatitis (1 paper, 2025). "In contrast, C5a signaling through C5aR1 promotes inflammation in models of allergic dermatitis." (PMID 40309766, 2025).
alveolitis (1 paper, 2025). "Importantly, blocking the C5a/C5aR1 signaling either before or after the initiation of fibrosis led to significant reductions in lung tissue cell numbers, alveolitis scores, Ashcroft scores, collagen deposition, and the expression of fibrosis-related genes, including Acta2, Col1a1, Col3, and Fn1." (PMID 40867551, 2025).
basophilic leukemia (1 paper, 2020). "SB290157 was previously shown to be devoid of C5aR1-antagonistic properties in human neutrophils or C5aR1-expressing rat basophilic leukemia cells." (PMID 33551801, 2020).
benign papillomas (1 paper, 2025). "C5aR1 expression was significantly higher in cSCC compared with that in AKs, cSCCIS, normal skin, or benign papillomas (SKs)." (PMID 40056975, 2025). "In conclusion, the current results show elevated C5aR1 expression in cSCC tumors, particularly at the invasive tumor edges and in stromal fibroblasts, compared with normal skin, benign papillomas (SKs), AKs, or cSCCIS." (PMID 40056975, 2025).
brain infarct (1 paper, 2019). "In a mouse model of 1-hour MCAO, C5aR1 deficiency or C5aR1 antagonist treatment reduced brain infarct volume and improved neurological function." (PMID 31011487, 2019).
cardiac arrest (1 paper, 2025). Cessation of breathing and/or cardiac function. "In a cardiac arrest model, C5a-C5aR1 engagement drove excessive neuronal autophagy by inhibiting the pro-survival PI3K/Akt/mTOR pathway." (PMID 41415286, 2025).
cholesteatoma (1 paper, 2022). A pathologic process characterized by the proliferation of keratinizing squamous epithelium resulting in the accumulation of keratin and cells in the middle ear and/or mastoid. "However, in our own middle ear expression dataset from the same patients, all 12 genes were DEGs for cholesteatoma: RTN4, RAB5A, CRYBG1, RGS22, HEPHL1, and SPTLC3 were upregulated, while APBB1IP, BHLHE41, ARID3A, C5AR1, CPT1B, and FAM227A were downregulated." (PMID 36699445, 2022).
chronic pyelonephritis (1 paper, 2016). "To conclude, this study is the first to define a novel and important role of C5aR1 in the pathogenesis of experimental chronic pyelonephritis." (PMID 27370410, 2016).
cognitive (1 paper, 2022). "Further support of a protective role of a C5aR1 antagonist is the rescue of the excessive synaptic loss and decreased AD-like pathology in 2 other mouse models of AD that correlates with memory loss and cognitive decline parameters seen in human AD." (PMID 35978440, 2022).
cystitis (1 paper, 2022). Inflammation of the urinary bladder. "By using a murine model of cystitis combining gene ablation and pharmacological blockade of C5aR1, we demonstrate that the C5a/C5aR1 axis also plays a pathogenic role in bladder infection." (PMID 35433513, 2022).
diabetic retinopathy (1 paper, 2023). "Due to the established role of CCs in complement activation, and the emerging evidence linking the complement system to progression of diabetic retinopathy, expression of the gene encoding complement receptor, C5AR1, and formation of MACs were analysed in CC-treated HREC." (PMID 37311879, 2023).
encephalitis (1 paper, 2025). An acute inflammatory process affecting the brain parenchyma. "Therefore, our findings demonstrate that targeting C5aR1 has potential therapeutic value for treating EV-A71 encephalitis." (PMID 39679722, 2025). "Similarly, activation of the C5a–C5aR1 axis has been detected in other models of viral encephalitis, such as models of Zika virus, Middle East Respiratory Syndrome Coronavirus, and HIV-1 infection." (PMID 39679722, 2025). "However, the potential role of the C5a–C5aR1 axis in EV-A71 encephalitis remains largely elusive." (PMID 39679722, 2025).